TG (thyroglobulin)
Diseases named in the same sentence as TG in open-access papers (continued):
Sharing a sentence is not in itself a finding about the gene and the disease.
thyroid (continued). "IgG2b thyroglobulin antibodies correlate with thyroid lesions and could therefore represent a biomarker for predicting thyroiditis." (PMID 35572553, 2022). "Additionally, the thyroglobulin-immunopositivity of the splenic neoplastic cells reinforced a thyroid histogenesis." (PMID 35681825, 2022). "Elevated thyroglobulin (Tg) levels during the phase of thyrotoxicosis and decreasing during the subsequent hypothyroidism have been observed in nivolumab-induced destructive thyroiditis." (PMID 34771441, 2021). "The existence of thyroid autoimmunity (e.g. positive anti-thyroid (anti-TPO or anti-thyroglobulin) antibodies and/or borderline levels of TRAb) at the time of treatment is another risk factor at least for Graves’ disease induced by high-dose internal irradiation." (PMID 29069397, 2018). "The genes responsible for autoimmune thyroid diseases could be categorized as either thyroid-specific types (e.g., thyroglobulin and TSH receptor) or immune-modulating types (e.g., Forkhead box P3 (FOXP3), CD25, CD40, CTLA-4, and HLA)." (PMID 29884162, 2018). "We also discuss the differential diagnostic challenges when faced with a thyroid malignancy that is negative for thyroglobulin." (PMID 27774331, 2016). "High levels of thyroglobulin accompanied the thyroiditis episodes." (PMID 25622640, 2015). "Because tumour specimens contain naturally variable amounts of blood proteins, and in the case of thyroid specimens, thyroglobulin, a simple protein quantitation assay would be insufficient for normalising loading quantities which is a requirement for accurate quantitation." (PMID 25880590, 2015). "The levels of thyroglobulin (Tg) can be elevated in many thyroid diseases." (PMID 25213012, 2014). "T4(2553) (T4 positioned at amino acid 2553) was the first reported thyroiditis-associated thyroglobulin peptide." (PMID 25050783, 2014). "Autoantibodies to thyroid peroxidase (TPO) and thyroglobulin (Tg) are reflections of thyroid disease rather than causative agents." (PMID 22530160, 2012). "Negativity of TTF-1 and thyroglobulin of tumour cells might be helpful in metastatic squamous cell carcinoma in the differentiation from the primary squamous cell carcinoma of the thyroid that reported exceptionally." (PMID 22933935, 2011). "However, if thyroglobulin levels increase or remain elevated, it may indicate the presence of residual thyroid tissue or recurrence of the disease." (PMID 39744583, 2025). "This study evaluated the diagnostic utility of thyroid function markers and contrast-enhanced ultrasound (CEUS) features in differentiating follicular thyroid adenoma (FTA) from follicular thyroid carcinoma (FTC), focusing on a novel parameter: the thyroglobulin-to-tumor volume ratio (Tg/Vol ratio)." (PMID 40708719, 2025). "However, some studies suggest that the presence of thyroid auto-antibodies, such as anti-thyroglobulin and anti-thyroid peroxidase, prior to starting ICI therapy may be associated with higher risk of developing thyroid-related irEEs." (PMID 37251665, 2023). "However, the tumor was unequivocally negative for thyroid-associated markers such as TTF1, PAX8 and thyroglobulin, setting it apart from other thyroid-related salivary gland tumors that are not uncommonly positive for one or several of these proteins." (PMID 32519264, 2021). "The tumor expressed thyroid markers (TTF-1, PAX-8, thyroglobulin) and renal cell markers (colloidal iron, parvalbumin, CD117) with peripheral mitochondrial accentuation by anti-mitochondrial staining." (PMID 41518426, 2026). "Regarding the thyroid antibodies, 55.22% of children had positive anti-TPO Abs and 43.28% had positive anti-TG Abs." (PMID 41044753, 2025). "Pathological examination and IHC analysis provide conclusive evidence for diagnosis, in which the tumor’s positive response to thyroid-specific markers, such as TTF-1, PAX8, and thyroglobulin, is key to diagnosis." (PMID 41244794, 2025).
thyroid (continued). "By using thyroid‐specific markers such as thyroglobulin and TTF‐1, IHC helps confirm the presence of thyroid tissue within ovarian tumors, distinguishing MSO from other ovarian neoplasms." (PMID 41356641, 2025). "All patients tested positive for autoimmune markers, with one showing hypergammaglobulinemia and three testing positive for thyroid autoantibodies–anti-TPO, anti-thyroglobulin (anti-TG), and anti-thyroid receptor." (PMID 40740211, 2025). "The rationale for its use is twofold: to exclude an occult cervical thyroid primary, and to enable RAI therapy and thyroglobulin-based surveillance if needed." (PMID 40370908, 2025). "Our patient also exhibited thyroiditis, which aligns with evidence that Borrelia spirochetal proteins share antigenic properties with thyroid-related proteins such as the TSH receptor, thyroglobulin, and thyroid peroxidase." (PMID 40161058, 2025). "Serum antibodies against thyroid antigens, primarily thyroperoxidase (TPO) and thyroglobulin, play a crucial role in confirming the autoimmune nature of the disease." (PMID 38505448, 2024). "In the first mouse model of αPD-1-induced thyroiditis, CBA/J immune-competent mice were immunized with human thyroglobulin (Tg) followed by treatment with αPD-1." (PMID 37445704, 2023). "Our findings suggest that there is a genetic relationship between the CTLA-4 (+55A/C) genotype and the seropositivity against thyroid autoantigens, such as anti-thyroid peroxidase (ATPO) and anti-thyroglobulin antibodies (ATG)." (PMID 37568880, 2023). "The patient's thyroid autoantibodies were tested positive at the time of thyroiditis with a TPO antibody of >900 and a thyroglobulin antibody of 1:20." (PMID 38259857, 2023). "The 11 selected thyroid-specific RNA transcripts (TPO, TG, GFRA2, IYD, PDE8B, WDR86, C16orf89, DGKI, DIO2, TSHR, and PAX8) were amplified from healthy volunteers and thyroid patients." (PMID 34512731, 2021). "Most patients with thyroiditis are usually positive for antibodies such as thyroid peroxidase (TPO) and/or thyroglobulin (Tg) antibodies." (PMID 33391917, 2020). "In our study’s thyroiditis cohort, of the 49 patients tested for TPO/TG Ab, only 18 had positive titers." (PMID 30693099, 2019). "Considering thyroid function, 389 (29.9%) of mothers had a positive family history of thyroidal disease, while 165 (12.7%) and 87 (6.7%) women had elevated levels of anti-TPO and anti-TG antibodies, respectively." (PMID 22175032, 2011). "Although thyroid autoantibodies (anti-thyroid peroxidase, anti-thyroglobulin) were not assessed due to cost limitations, the clinical profile was consistent with postpartum thyroiditis." (PMID 41496136, 2026). "It should be emphasized that the auto-antibodies determined in the diagnosis of selected thyroid diseases and thyroglobulin serum concentration were not measured in the current study." (PMID 39860610, 2025). "The absence of any nuclear labelling against TTF1, together with a negative assessment against thyroglobulin, disregards a thyroid origin of the neoplasm." (PMID 41180242, 2025). "Another study mainly assessed the frequencies of serum gastric parietal cell antibody (GPCA), thyroglobulin antibody (TGA), and thyroid microsomal antibody (TMA) positivities in 30 atrophic glossitis (AG)-positive RAS/BD (AGþRAS/BD) and 33 AG-negative RAS/BD (AG־RAS/BD) patients." (PMID 40547274, 2025). "IHC staining of the tumor in the neck showed diffuse expression of PAX8 and TTF1, indicating thyroid origin, and negative staining for thyroglobulin, calcitonin, PTH, and GATA3, which support a diagnosis of an oncocytic poorly differentiated thyroid carcinoma." (PMID 40277780, 2025). "Serum thyroid function tests were performed, including thyroid-stimulating hormone (TSH), free thyroxine (FT4), and antithyroid antibodies (TAAs), including anti-thyroglobulin antibodies (TgAb), anti-thyroperoxidase antibodies (TPOAb), and TSH receptor antibodies (TRAb)." (PMID 41044072, 2025).
thyroid (continued). "Thyroid-specific tumor and autoimmunity markers (calcitonin, thyroglobulin, anti-thyroglobulin antibodies, and thyroid peroxidase antibodies) were not included in the comparative analyses due to their non-uniform availability across the retrospective cohort." (PMID 41595547, 2025). "Thyroid abnormality was assessed through the current history of thyroid disease and laboratory tests - thyrotropin (TSH), free thyroxine (FT4), antithyroid peroxidase (anti-TPO) and antithyroglobulin (anti-TG) antibodies." (PMID 37598033, 2024). "A prospective study that aimed to compare the incidence of thyroid diseases over six years found a significant increase in subclinical hypothyroidism, TPO, and thyroglobulin antibody (Tg Ab) positivity, and thyroid ultrasound hypo-echogenicity among psoriatic arthritis patients, particularly women." (PMID 39337081, 2024). "FNA at clavicle mass confirmed a thyroid malignancy (positive for TTF1, thyroglobulin)." (PMID 38791947, 2024). "It should also be emphasized that autoantibodies used in the diagnosis of thyroid disease and thyroglobulin serum levels have not been determined in the study population." (PMID 39336486, 2024). "Higher levels of Interleukin IL-1β, IL-2, and granulocyte-macrophage colony-stimulating factor (GM-CSF) at baseline, an early increase in serum thyroglobulin and thyroid autoantibodies, and an early decrease of IL-8, G-CSF, and MCP-1 were found in the ICI-induced thyroid disease group." (PMID 37251665, 2023). "After excluding thyroid peroxidase antibody (TPO-Ab) positive and/or thyroglobulin antibody (TG-Ab) positive women, previous thyroid disease, a lack of iodine intake, reference values were calculated by 2.5th to 97.5th percentiles." (PMID 33305315, 2021). "This improvement seems to have had a positive impact on maternal thyroglobulin, but did not influence maternal thyroid morbidity." (PMID 33620551, 2021). "Ultrasound at the age of 9 years, however, detected no thyroid tissues and thyroglobulin was 8.7 ng/mL while TSH was elevated, indicating thyroid hypoplasia." (PMID 34946811, 2021). "Third, FT3, FT4, and TSH are routinely measured upon admission to the ICU, but thyroid-related antibody, thyrotropin receptor antibody, thyroglobulin, rT3, and thyroid B-ultrasound are not routinely done." (PMID 32766311, 2020). "Thyroid function showed subclinical hypothyroidism, calcitonin was normal, serum thyroglobulin levels were low, and anti-thyroid antibodies were absent." (PMID 33101736, 2020). "In addition, the development of autoantibodies against thyroid proteins mainly thyroid peroxidase (TPO), thyroglobulin (Tg), and thyroid stimulating hormone (TSH) receptor can lead to thyroid disorders." (PMID 31320934, 2019). "Then, in order to validate the tumor suppressor role of PATZ1 in thyroid carcinogenesis in vivo, we crossed a mouse model of PTC, carrying the RET/PTC1 oncogene under the thyroid-specific control of the bovine thyroglobulin promoter with mice knockout for the Patz1 gene." (PMID 29584698, 2018). "A small number of patients in both groups had evidence of autoantibodies against thyroid (anti-microsomal or anti-thyroglobulin) but lacked evidence of clinical disease (IPEX n = 3, IPEX-like n = 5)." (PMID 30443250, 2018). "Anti-thyroglobulin autoantibodies, as well as thyroid hormones, were measured to define thyroid abnormalities, but a detailed definition of thyroiditis was not provided." (PMID 29069397, 2018). "In patients with thyroid nodules, routine measurement of serum thyroglobulin is not recommended as it can be elevated in many thyroid diseases and is neither specific nor sensitive for thyroid cancer." (PMID 28702251, 2016). "The presence of thyroid autoantibodies to thyroid peroxidase (TPO-Ab) and thyroglobulin (Tg-Ab) is common in women of reproductive age and is indicative of thyroid inflammation and an increased risk of developing autoimmune thyroid disease, such as Hashimoto’s thyroiditis." (PMID 25524327, 2016).
thyroid (continued). "Because thyroglobulin and thyroperoxidase are the two primary antigens in autoimmune thyroiditis, patients who suffered from CLT would make corresponding autoantibodies against thyroid-specific antigens." (PMID 25179111, 2014). "Our patient had negative thyroid peroxidase antibodies, positive thyroglobulin antibodies, and past history of thyroid disease." (PMID 24987536, 2014). "In HT, the immune system mounts an autoimmune response against thyroid antigens, leading to chronic inflammation, predominantly mediated by autoreactive T lymphocytes and the production of anti-thyroid peroxidase (anti-TPO) and anti-thyroglobulin (anti-TG) antibodies." (PMID 40722630, 2025). "In thyroid malignancies, excluding well-differentiated thyroid cancers, the paired box gene 8 (PAX-8) protein is considered a more sensitive indicator of thyroid origin than TTF-1 or thyroglobulin; however, PAX-8 is present in limited quantities in primary squamous cell carcinomas." (PMID 40061900, 2025). "Beyond the increased prevalence of Hashimoto’s thyroiditis in PCOS, available research has also investigated the presence of its characteristic autoantibodies (anti-TPO and anti-thyroglobulin (anti-TG)) in euthyroid women with PCOS or those without a diagnosis of thyroid disease." (PMID 40943118, 2025). "Due to the remaining parts of both thyroid lobes, the thyroglobulin value could not be addressed as a tumour marker of persistent thyroid malignancy." (PMID 39336834, 2024). "One patient who discontinued treatment because of silent thyroiditis related to ropeginterferon alfa-2b had no history of thyroid dysfunction and was positive for anti-thyroid peroxidase antibodies and negative for anti-thyroglobulin antibodies at baseline." (PMID 38951434, 2024). "Utilizing the most recent assays, antibodies (thyroid peroxidase autoantibodies, TRAb, thyroglobulin specific antibodies) are proving to be a potent marker (if not pathogen) of thyroid disorders, and the subsequent months are expected to provide further insight into its function in this state." (PMID 36514581, 2022). "The presence of thyroid anti-TPO antibodies was found positive in 40% of hypothyroid pregnant females in an Indian epidemiological study, while an Iranian study reported 12.8 and 8.5% prevalence of anti-TPO and anti-TG antibody positivity in their population of 600 pregnant females." (PMID 33588796, 2021). "Women with non-toxic goitre were defined as simultaneously having a non-toxic goitre diagnostic code [E04.x (Other non-toxic goitre)] and a thyroid test code (thyroid stimulating hormone (TSH), free T3, free T4, anti-thyroid antibody, anti-thyroglobulin antibody, and neck ultrasound)." (PMID 30932000, 2019). "Ablation of IFN-γ, or IL-17, but not IL-4, in NOD.H2h4 mice demonstrated resistance to both thyroiditis and the generation of anti-thyroglobulin autoantibodies, indicating that both Th1 and Th17 cells are the T-cell subsets critical for the pathogenesis of iodine-induced AIT in these mice." (PMID 25050783, 2014). "Moreover, in our patient, tumor cells in the pleural effusion were positive for TTF-1 but negative for thyroglobulin on immunohistochemistry, which made it even more difficult to identify the origin of the malignant pleural effusion as being the thyroid." (PMID 25532447, 2014). "Anti-thyroglobulin, anti-thyroperoxidase antibodies, or both, are frequently detected in subjects with hypo- or hyperthyroidism of autoimmune origin, and can also be found in patients without any sign of thyroid disease." (PMID 19941670, 2009). "Of the 14 patients with both classic Whipple’s disease and discrepancies in the TSH serum levels, 13 patients lacked positive anti-thyroglobulin and anti-thyroperoxidase antibodies (the 14th patient could not be tested because of an insufficient amount of serum) excluding a thyroiditis." (PMID 24996424, 2014).
thyroid (continued). "Third, our dataset did not include information on thyroid antibody levels (e.g., TPO and thyroglobulin antibodies) or autoimmune thyroid disease diagnoses." (PMID 39941590, 2025). "Antibodies anti-thyroperoxidase, anti-thyroglobulin, and anti-TSH receptor were within the normal range and the patient had no family history of thyroid disease." (PMID 39648292, 2024). "In the second sub-study, thyroid hormones (T3, T4, TSH) and thyroid auto-antibodies levels (anti-TG, anti-TPO) of 72 healthy subjects with no history of thyroid disease were examined before (D1) and one month after completion of the second dose (D50)." (PMID 35273575, 2022). "Patients with thyroiditis as expected had significantly higher values of thyroid autoantibody, anti-TPO, and anti-TG, as well as TSH, compared to MS without thyroiditis." (PMID 33132691, 2020). "Finally, in non-lactating women with postpartum thyroiditis, anti-TPO and anti-TG titers were found to be inversely correlated with vitamin D levels (p < 0.001)." (PMID 28303359, 2017).